SP1 (Sp1 transcription factor)
Diseases named in the same sentence as SP1 in open-access papers (continued):
Sharing a sentence is not in itself a finding about the gene and the disease.
cancer (continued). "Elevated levels of Sp1 have been associated with many cancers, indicating that Sp1 can potentially serve as a molecular target for cancer treatment and chemoprevention." (PMID 33995644, 2021). "With the evidence showing its association with tumorigenesis, SP1 also gets actively involved in several cancers." (PMID 34970121, 2021). "Overexpression of SP1 is associated with poor prognosis in many cancer types and SP1 is subject to regulation by various post-translational modifications." (PMID 35201498, 2021). "SP1 is one crucial transcription factor implicated in the modulation of multiple cancers; specifically, SP1 regulates the expression of genes that are related with the cell proliferation and metastasis of various tumors." (PMID 33431838, 2021). "On the other hand, the transcription factor Sp1, implicated in cancer cell growth and metastasis, is known to bind the DFS70/LEDGF promoter to activate its expression in various cell types (reviewed in Ref." (PMID 32127038, 2020). "Defects in the Sp1 transcriptional activities act as a cause for tumorigenesis in many types of cancers, such as ovarian, breast, and gastric cancer." (PMID 32050495, 2020). "Using immunoblotting and flow cytometry techniques, we reported that PEITC suppressed the cancer-associated transcription factor (Sp1) and a downstream multidrug resistance protein (P-glycoprotein) (both, p < 0.05)." (PMID 30818757, 2019). "Specific protein 1 (SP1) is associated with aggressive behavior, invasive clinical phenotype and poor clinical outcomes in various cancers." (PMID 30976063, 2019). "The upregulation of lncRNAs in cancer is associated with increased activities of oncogenic transcription factors such as c-Myc, SP1 and E2F1." (PMID 29416741, 2018). "Clinical data showed that ZEB2 expression was positively associated with Sp1 expression, and that the expression of both of these factors had prognostic significance for predicting survival in cancer patients." (PMID 29416649, 2018). "Identification of the lysine 639 on Sp1 as a specific target of TIP60 offers the possibility of a diagnostic tool for TERT-driven cancers." (PMID 29045464, 2017). "Mechanistically, elevated Sp1 levels lead to the expression of multiple oncogenic genes, causing progression of the cancers." (PMID 29088790, 2017). "The anti-cancer activity of TA is associated with the degradation of the specificity protein 1 (Sp1) transcription factor and the inhibition of expression of its downstream targets such as cMet, VEGF, and Survivin." (PMID 28099934, 2017). "Sp1 promotes a variety of cancer associated genes that are implicated in cell growth, differentiation, and apoptosis." (PMID 27009809, 2016). "Sp1 is known to be constitutively overexpressed in many cancers, and associated with poor prognosis." (PMID 27738323, 2016). "In this study, we find six pan-cancer subnetwork signatures associated with distinct common cancer mechanisms including cell cycle, SP1 regulations, immune response, extracellular matrix organization, muscle system process and angiogenesis." (PMID 27633916, 2016). "The results of these studies support the proposal that elevated Sp1 expression contributes to cancer development and progression and represents a potential risk of poor prognosis." (PMID 26763486, 2016). "A later study showed that HDAC4 became associated with Sp1 at the proximal p21 promoter, and promoted cancer cell growth via repression of p21 in an Sp1-dependent manner." (PMID 26441331, 2015). "So far, multiple studies have shown that the Sp1-dependent fraction of hypoxia-driven transcriptional activation is associated with the radioresistance of cancer cells." (PMID 26703734, 2015). "The enhancer overlaps ChIP-seq binding peaks of 8 transcription associated factors in A549 cells, including the enhancer marking p300 co-activator and other TFs such as c-Myc, Max, and SP1 which are linked to cancer development and growth." (PMID 24920305, 2014).
cancer (continued). "SP1 regulates a variety of cancer associated genes that are related to cell growth, proliferation, angiogenesis, migration, and apoptosis." (PMID 23437057, 2013). "Sp1 regulates several cancer associated genes associated with the cell cycle, proliferation, differentiation and apoptosis." (PMID 23403540, 2013). "In contrast, SNP285G>C (rs117039649), located 24 bp upstream of rs2279744, and in complete linkage disequilibrium with the SNP309G allele, reduces Sp1 recruitment and lowers cancer risk." (PMID 22558411, 2012). "One of these polymorphisms (SNP309T>G; rs2279744) facilitates Sp1 transcription factor binding to the promoter and is associated with increased cancer risk." (PMID 22558411, 2012). "Transcription factors, such as Sp1 bound to GC-rich sequences in promoter regions, are associated with cancer pathogenesis." (PMID 22984445, 2012). "Another two TFs (PAX5 and SP1) are involved in cell differentiation, which also is a cancer-associated process." (PMID 21857930, 2011). "Among these transcription factors, AP-2, SP1, and NF-kB are either well known or implicated by many studies to be associated with cancer progression." (PMID 19563622, 2009). "Numerous studies have documented that Sp1 activity and/or Sp1 expression levels are elevated in various human cancers and are associated with prognosis." (PMID 18577987, 2008). "Here, we describe a polymorphism in the RIL promoter that creates an Sp1/Sp3 binding site and protects against methylation in cancer." (PMID 18725933, 2008). "Increased Sp1 expression is consistently associated with poor outcomes in multiple malignancies, such as breast, lung, colorectal, pancreatic, and liver cancers, highlighting its critical role in cancer progression." (PMID 41596524, 2026). "Furthermore, Sp1 has also been shown to be associated with “contributing features” of cancer, namely, the inflammatory and unstable genome." (PMID 39228402, 2024). "Additionally, SP1 has been shown to promote carcinogenesis and cause metabolic reprogramming in a variety of cancer types." (PMID 39056681, 2024). "Our observation that the sensitivity of cancer cells to ionization radiation is increased in the presence of HDAC inhibitors further supports chromatin modification in the mechanism underlying SP-1-303 cytotoxic effects." (PMID 39008483, 2024). "SP1 is critical for early embryonic development, but its expression decreases with age and there is evidence that the transformation of normal cells to cancer cells is associated with the upregulation of SP1, SP3, and SP4." (PMID 37998757, 2023). "In sum, β-1,4-GalT-V gene transcription is regulated by Sp1, and the loss of regulation by Sp1 may contribute to aberrant cell proliferation and cancer." (PMID 38203654, 2023). "Furthermore, we confirmed that de novo methylation is precluded across cancers at CpGs lying in genomic regions enriched for TF binding signatures associated with SP1, CTCF, NRF1, GABPA, KLF9, and/or YY1." (PMID 35440061, 2022). "Interestingly, studies have shown that, similar to Creb3l1, the high expression of Sp1 is associated with poor prognosis in many cancers." (PMID 35803572, 2022). "Finally, 24 relevant studies reporting the association between SP1 expression and clinical indicators of cancers were included in this study." (PMID 34257529, 2021). "Therefore, PBMC genetically engineered to express sp1- and sp2-specific TCRs were co-cultured with a series of cancer cell lines that harbored the G12V mutation within the KRAS gene." (PMID 33875134, 2021). "In patient samples, Sp1 levels are associated with the survival of cancer patients." (PMID 33329003, 2020). "SP1 is over-expressed in various cancers and is associated with poor prognosis." (PMID 32432112, 2020). "Thus, the given literature suggests that major cancer-associated signaling pathways trigger Sp1 to activate various oncogenes and support the development and progression of OC." (PMID 32050495, 2020).
cancer (continued). "However, there have been no studies demonstrating EGR1-NAB2 regulatory mechanisms associated with Sp1 during cancer progression." (PMID 30845713, 2019). "Similarly, we extended this analysis strategy to other types of cancers and found that SP1 was the leading transcription factors associated with Ajuba in cancers of liver, colon and breast." (PMID 31101117, 2019). "Sp1 regulates cell survival, growth and angiogenesis by activating the transcription of specific target genes, and its abnormal expression is found to be associated with cancer development and major aggressiveness." (PMID 29865240, 2018). "The association between ZEB2 and Sp1 could also be targeted to develop novel therapies against cancer." (PMID 29416649, 2018). "According to these data, Sp1 O-GlcNAcylation, increasing its activity and stability, may be directly involved in the cancer metabolic rewiring associated with cancer onset." (PMID 29865240, 2018). "However, factors which regulate Sp1 expression in cancers and the underlying mechanism are still unclear." (PMID 29262634, 2017). "Sp1 has been shown to be upregulated in various cancers and is associated with poor prognosis." (PMID 28099934, 2017). "Sp1, a cancer-associated transcription factor, was among these proteins." (PMID 26511642, 2016). "Moreover, activation of Sp1 is implicated in an ample variety of cancer biological processes, including sustained proliferation, replicative immortality and induction of angiogenesis, invasion and metastasis." (PMID 27806345, 2016). "Sp1 expression is associated with bad prognosis in gastric cancers, and has been reported to be overexpressed and/or over-activated in a number of human cancers at late stage." (PMID 25738304, 2015). "Our evidence suggested that dysregulation of Sp1 signalling pathway by miRNAs is an important mechanism underlying cancer procession, and may serve as potential treatments for modulating this pathway in cancers." (PMID 25639535, 2015). "Thus, it is clear that Sp1 plays multiple roles in the progression of cancers exposed to oxygen deficiency." (PMID 26703734, 2015). "Sp1 was associated with the third top scoring transcriptional network in tumor tissue after the well-known cancer-related transcription factor c-Myc and also CREB-1 that was recently found to be associated with OVCA cell line platinum sensitivity and overall survival." (PMID 25265318, 2014). "Indeed, a precedential case has been described for the major histocompatibility complex class II-associated invariant chain, where Sp1 and NF-Y cooperatively activate the gene in cancer cell lines." (PMID 22412893, 2012). "In addition to the cancer types described here, Sp1 is implicated in other cancer types and in tumorigenesis by mediating the expression of many oncogenes." (PMID 23148884, 2012). "To ascertain whether there are mutations in the Sp1 element, we sequenced the entire region analysed above in the cancer cell lines and tissues." (PMID 22022465, 2011). "Interestingly, Sp1 is a known regulator of two cancer-associated genes in the cadmium-associated networks." (PMID 21457566, 2011). "Also, Sp1 site-dependent transcription is involved in many signal transduction pathways linked to cancer progression." (PMID 21731707, 2011). "SP1 encodes the transcription factor (TF) Sp1, that has been associated with poor prognosis for various tumors; moreover, functional studies demonstrated that Sp TFs regulate the expression of genes responsible for cancer cell growth, survival, migration/invasion, inflammation, and drug resistance." (PMID 32664456, 2020). "Besides, highly expressed SP1 was associated with the poor prognosis in cancer patients." (PMID 29654167, 2018). "Since Sp1 is a critical transcription factor which regulates several cancer associated genes associated with cell survival, proliferation and angiogenesis, the abnormal expression or increased binding activity of Sp1 may contribute to tumor development and progression." (PMID 23403540, 2013).
cancer (continued). "Overall, this data suggests that SP1 controls several features of metastatic cancer cells in vitro and in vivo." (PMID 39748426, 2025). "Considering that, despite the momentum mithralogs have gained as promising therapeutics for some cancers, they and other Sp1 inhibitors remain a relatively un-applied class of drugs due to high toxicity." (PMID 40143226, 2025). "Mechanistically, ANXA8 interacts with SP1 to promote the transcription of pyrophosphatase 1, thereby suppressing the TCA cycle, activating cancer-associated fibroblasts, and facilitating aberrant ECM deposition." (PMID 40862051, 2025). "In conclusion, our integrated analysis of scRNA-seq and metastatic scoring data reveals the opposing roles of SP1 and KLF5 in regulating metastasis by governing the underlying gene expression program in cancer cells." (PMID 39748426, 2025). "Mechanistically, FASN, which is upregulated in CRC tissues, drives cancer cell proliferation, metastasis, and PC metabolism through the SP1/PLA2G4B axis, subsequently suppressing the antitumor response of natural killer (NK) cells in a PC-dependent manner." (PMID 40148316, 2025). "Specificity proteins (Sp), members of the Sp/Kruppel-like factor family, demonstrate elevated expression patterns across various tumor and cancer cell lineages, with particularly pronounced expression observed for Sp1, Sp3, and Sp4." (PMID 41007866, 2025). "Sp1 upregulates oncogenic targets and suppresses tumor suppressor genes, contributing to the malignant potential in cancer-specific stem cells." (PMID 40869407, 2025). "High levels of Sp1, Sp3, and Sp4 contribute to cancer cell development, survival, and migration to tissues, including the pancreas." (PMID 40758706, 2025). "Extensive literature reports that SP1 is overexpressed in approximately 90% of malignant tumors, particularly in cancer cells resistant to radio- and chemotherapy." (PMID 41562084, 2025). "The Sp1/FGF-BP1/FGF2/FGFR axis highlights how Sp1 governs the transcriptional pathways that promote cancer-specific stemness." (PMID 40869407, 2025). "Due to its role in regulating key cancer-related genes, SP1 has emerged as a therapeutic target in CRC." (PMID 40869407, 2025). "Ligands for PPARƔ, AR, PR and RARα activate p21 expression in cancer cells through interactions of NR/Sp1 or NR/Sp4 with two or more members of the Sp1–6 binding sites in the proximal region of the p21 gene promoters." (PMID 39858066, 2025). "Previous studies have demonstrated that Sp1 is aberrantly expressed and plays important roles in cancer by stimulating the growth of tumor cells." (PMID 39982662, 2025). "Given Sp1’s tumorigenic role, suppression of Sp1 has been shown to promote apoptosis in cancer cells." (PMID 40869407, 2025). "Because of its binding sites present in a large number of genes, it is likely that the downregulation of Sp1 would have a profound effect on the survival of cancer cells." (PMID 40723802, 2025). "Our discovery of the YAP/TAZ/SP1-VISTA regulatory axis in CRC is consistent with the immune evasion function of YAP/TAZ in human cancers." (PMID 39875519, 2025). "SP1 is degraded in normal cells, but it is overexpressed in cancer cells, contributing to the proliferation and survival of cancer cells." (PMID 39860065, 2025). "Notably, SP1-enriched promoters were predominantly associated with known oncogenes, including Ahcyl2, Bcl3, and Sp1 itself, suggesting that SP1’s oncogenic potential may arise from its role in regulating transcription of cancer-associated genes." (PMID 40884402, 2025).
cancer (continued). "PPARƔ primarily inhibits the growth of cancer cells; emodin decreases IGFBP1; cladosporol, rosiglilazone and a bis-indole PPARƔ ligand induce p21; and thiazolidinediones (TZDs) decrease an insulin receptor via PPARƔ/Sp1 in cancer cell lines." (PMID 39858066, 2025). "Further experiments showed that SP1 is critical for cancer cell survival, invasive growth and metastatic colonisation, highlighting its critical importance in metastasis at the pan-cancer level." (PMID 39748426, 2025). "Although generally considered a ubiquitous TF, SP1 plays a crucial role in cell-type-specific gene expression programs and is frequently overexpressed in various cancers." (PMID 40884402, 2025). "This upregulation of FoxO3a enhances tumor volume and progression, highlighting the role of SP1 in cancer growth." (PMID 40754247, 2025). "Over the past forty years, the role of SP1 in cancer has been well documented in almost every aspect of the “hallmarks of cancer”." (PMID 39875519, 2025). "Conversely, overexpression of SP1 in lowly metastatic cancer cells was sufficient to confer a migratory behaviour which accompanied upregulation of these markers both at the RNA and protein levels." (PMID 39748426, 2025). "Interactions of NR4A2 and NR4A3 with Sp1/Sp4 to activate or deactivate gene expression have not been characterized; however, there is considerable evidence that NR4A1 interacts with Sp1 and Sp4 to regulate several genes in cancer cell lines." (PMID 39858066, 2025). "Our data demonstrate that Niraparib-induced resistance is intricately linked to the SP1-SE-SPHK1 axis, highlighting the critical interplay between epigenetic regulation and metabolic adaptation in cancer cells." (PMID 41304867, 2025). "In non-cancer cells, RARα/Sp1 enhances induction pyruvate dehydrogenase kinase 4 (PDK4), guanylyl cyclase/atrial natriuretic peptide receptor-A (Npr1), apelin and TNFα-inducible protein 3-interacting protein 1 (TNIP1)." (PMID 39858066, 2025). "In this regard, pharmacological inhibition of SP1 is an attractive strategy aimed at overcoming radioresistance in HNCs or other cancer types." (PMID 39800760, 2025). "ATM is the key mobilizer of cellular reaction to DNA impairment; Sp1 can contribute to DNA restore response and regulate cancer through ATM-mediated phosphorylation." (PMID 39228402, 2024). "The transcription factor SP1 aroused our interest based on its important roles reported in several human cancers 19,20." (PMID 38356702, 2024). "It is well known that Myc, Sp1, BMI1, and MALAT1 are cancer stem cell (CSC) markers implicated in chemoresistance in NSCLC." (PMID 38125755, 2024). "Sp1 is overexpressed in cancer cells and, in most cases, activates genes that enhance proliferation, invasion, and chemoresistance." (PMID 38540340, 2024). "Our study unravels an acetate-mediated mechanism to epigenetically regulate polyamine homeostasis in cancer cells, and acetylation of SP1 protein, impacting its stability and DNA-binding properties." (PMID 38429478, 2024). "This suggests that these miRNAs affect cancers via their activity to either induce or suppress the expression of SP1, MYC, and HIF1A." (PMID 39590335, 2024). "In this article, we summarize the molecular structure and function of Sp1 protein, in addition to the regulatory mechanism by which PTMs affect cancer initiation and progression." (PMID 39228402, 2024). "The intricate functionality of Sp1 is evidenced by its ability to modulate key genes that impact the top ten characteristics of cancer; It affects eight major features of cancer by regulating several key genes." (PMID 39228402, 2024). "Therefore, an in-depth examination of the PTMs of Sp1 protein and its impact on cancer diseases will provide novel perspectives for understanding the molecular mechanism underlying cancer incidence and emphasize new objectives and approaches for cancer prevention, detection, and therapy." (PMID 39228402, 2024).